NDRG2 (NDRG family member 2)
Diseases named in the same sentence as NDRG2 in open-access papers (continued):
Sharing a sentence is not in itself a finding about the gene and the disease.
tumor (continued). "NDRG2 has been identified as a specific tumor suppressor gene." (PMID 26506239, 2016). "Interestingly, inhibitors of p38 MAPK have attracted attention in research related to cancer treatment; however, NDRG2 exerts anti-tumor effects via the activation of p38 MAPK." (PMID 26506239, 2016). "Collectively, NDRG2 promotes tumor cell apoptosis but inhibits the apoptosis of normal cells." (PMID 26506239, 2016). "There is a trend for NDRG2 level to decrease with tumor invasion depth and histology grading." (PMID 26506239, 2016). "NDRG2 may be a tumor biomarker, and the combination of NDRG2 with other molecules, such as CD24 and HOXD1, may yield more specific or sensitive biomarkers." (PMID 26506239, 2016). "Mutational analyses of the entire NDRG2 coding sequence have not revealed tumor-associated DNA sequence alterations." (PMID 26506239, 2016). "The regulatory role and molecular mechanism of NDRG2 in tumor suppression, especially in tumor metabolic reprogramming, remain unclear." (PMID 26317652, 2015). "In addition, rescue experiments in ITLN1 over-expressed or silenced NB cells showed that restoration of NDRG2 expression prevented the tumor cells from ITLN1-mediated changes in these biological features." (PMID 25889839, 2015). "Understanding the mechanisms involved in cancer cell energy metabolism may provide a reasonable interpretation for the function of NDRG2 as a tumour suppressor." (PMID 24636131, 2014). "Next, we sought to explore the regulatory mechanism of NDRG2 in tumour glucose metabolism." (PMID 24636131, 2014). "The present study investigated whether an association between NDRG2 expression and the intracellular energy regulator AMPK plays a role in tumor cell apoptosis." (PMID 25061501, 2014). "In addition, obvious positive NDRG2 staining was detected by IHC in tumours excised from mice in the 2 × 109 PFU Ad-NDRG2 group." (PMID 24636131, 2014). "In view of these findings, NDRG2 was supposed to be a candidate tumor suppressor gene that may be developed to a new anti-tumor target." (PMID 23307246, 2013). "Moreover, in a nude mouse model of ESCC, Ad-NDRG2 treatment achieved a sustained and significant arrest of tumour growth, and expression of cyclinD1 and Ki67 was lower in tumours excised from mice in the Ad-NDRG2 group." (PMID 23800335, 2013). "Recently, several reports suggest that NDRG2 might play a vital role in inhibition of tumor metastasis." (PMID 24146910, 2013). "In addition, our previous studies demonstrated that MSP58 interacted with N-myc downstream-regulated gene 2 (NDRG2) in nucleus, which exerted important functions in cell differentiation and tumor proliferation." (PMID 22773039, 2012). "It should be noted that NDRG2 has been proposed as a potential tumor suppressor." (PMID 22920753, 2012). "In another study, we found adriamycin enhanced NDRG2 expression in several tumor cell lines." (PMID 22920753, 2012). "Alternatively, the observed correlation of MYC and NDRG2 mRNA expression in breast tissue may result from a shared regulatory mechanism of these genes in the normal and tumor samples tested." (PMID 21226903, 2011). "Recently, NDRG2 has been reported to act as a tumor suppressor." (PMID 21676268, 2011). "However, we observed only a weak correlation between MYC and NDRG2 mRNA expression in normal and tumor samples from breast tissue, indicating that MYC and NDRG2 are co-regulated." (PMID 21226903, 2011). "One third of all tumor samples analysed showed down-regulation of NDRG2 mRNA levels by 2-fold or more compared to corresponding normal tissue, suggesting that either the regulators of NDRG2 are generally affected or that NDRG2 is often inactivated in tumors." (PMID 21226903, 2011). "Based on our current understanding, NDRG2 is a candidate tumor suppressor gene." (PMID 21226903, 2011).
tumor (continued). "Our data from 19 different cancers indicates that NDRG2 is up-regulated in around 8% of all tumors examined, unaltered in 62% of all cases and that approximately a third of the tumor samples show down-regulation of NDRG2 compared to the corresponding normal tissue." (PMID 21226903, 2011). "Furthermore, high NDRG2 expression levels correlate positively with tumor differentiation and negatively with clinical parameters relevant to tumor metastasis." (PMID 22110735, 2011). "Furthermore, our observations indicate that other tissues such as cervix and testis can have lower levels of NDRG2 mRNA in tumor tissue compared to normal tissue." (PMID 21226903, 2011). "An evaluation of NDRG2 mRNA expression level, depending on tumour stage in TNM classification was performed for two groups: the first group included pT1 cases (Group pT1, n = 12) and the second one included (because of the small number) combined cases of pT2, pT3 and pT4 (Group pT2-pT4, n = 4)." (PMID 20804549, 2010). "The findings highlight the usefulness of combining gene expression patterns and epigenetic data to identify tumour biomarkers, and suggest that NDRG2 silencing might bear influence on tumour invasiveness, being associated with a more advanced stage." (PMID 19257893, 2009). "We initially identified human NDRG2 as a candidate tumor suppressor gene." (PMID 18940011, 2008). "NDRG2 also exerts important functions in cell differentiation and tumor suppression." (PMID 18940011, 2008). "Finally, comparing the level of NDRG2 mRNA in normal tissue far (normal distant) and close (normal adjacent) to that of the tumor in the surgical specimens of CRC patients showed a statistically significant difference (p < 0.001) in both cases." (PMID 17935612, 2007). "In order to examine whether the risk of carcinoma is affected by changes in the microenvironment, expression levels of NDRG2 in the lesion were compared to normal adjacent tissue as well as to normal tissue distant from the tumor." (PMID 17935612, 2007). "Additionally, the tumor suppressor NDRG2 influences TAM polarization through NF-κB signaling." (PMID 40764998, 2025). "Although NDRG2 operates as an adaptor protein to mediate the interaction between kinases and phosphatases, which is essential in regulating cell signaling related to tumor metastasis, the molecular mechanism of NDRG2 as an adapter protein does not seem to be fully elucidated." (PMID 36012631, 2022). "NDRG2-overexpressing mouse 4T1 cells showed less Smad-dependent-transcription and lower levels of active aTGF-β, invasiveness in vitro and metastatic activity in vivo than control cells, suggesting that NDRG2 suppresses tumor metastasis by attenuating active aTGF-β production and signaling." (PMID 33478130, 2021). "Upregulating NDRG2 expression could inhibit endothelial cell proliferation and tumor angiogenesis." (PMID 34013046, 2021). "Therefore, NDRG2 is an important suppressor in tumor metabolic reprogramming." (PMID 31523182, 2019). "Moreover, the use of glucocorticoids may induce NDRG2 expression, but whether this will contribute to the regulation of tumor development and progression remains unknown." (PMID 26506239, 2016). "Therefore, NDRG2 is regarded as a tumor-suppressor gene that represses the PI3K-Akt pathway." (PMID 27447861, 2016). "Thus, the tumor-suppressive action of NDRG2 may be attributed to its ability to compromise MYC-driven metabolic reprogramming in cancer cells." (PMID 27447861, 2016). "Furthermore, NDRG2 levels tend to decrease with tumor invasive depth and increasing grade." (PMID 26506239, 2016). "Evidence suggests that NDRG2 may act as a tumor suppressor in various cancers." (PMID 27072586, 2016).
tumor (continued). "NDRG2 exerts anti-tumor effects by regulating various processes, including promoting apoptosis, arresting cell proliferation by influencing cell cycle, inhibiting angiogenesis and suppressing energy metabolism, which may provide attractive strategies for therapeutic interventions in human cancer." (PMID 26506239, 2016). "In addition, NDRG2 reportedly inhibits proliferation of certain tumor cells." (PMID 27072586, 2016). "NDRG2 suppresses the expression of transporters and catalytic enzymes, which provide bioenergy and biomaterials for cancer cell proliferation and tumor progression, thereby playing an important role in inhibiting glycolysis and glutaminolysis and restraining tumor cell metabolism." (PMID 26506239, 2016). "However, whether NDRG2 can be used as a candidate biomarker for tumor incidence or prognosis requires further investigation." (PMID 26506239, 2016). "In addition, we found that ITLN1 induced the KLF4 expression via inactivation of PI3K/AKT signaling, which was required for ITLN1-mediated up-regulation of NDRG2 in NB cells, suggesting the tumor suppressive roles of ITLN1/KLF4/NDRG2 axis in the tumorigenesis of NB." (PMID 25889839, 2015). "Moreover, NDRG2 overexpression inhibited tumor growth in vivo." (PMID 26317652, 2015). "Moreover, restoration of NDRG2 expression prevented the NB cells from ITLN1-mediated changes in the growth, invasion, and metastasis, suggesting that ITLN1 may exert its tumor suppressive functions, at least in part, through up-regulating NDRG2 in NB." (PMID 25889839, 2015). "However, very little information is available regarding the function of NDRG2 in tumour metabolism." (PMID 24636131, 2014). "However, NDRG2 expression decreased progressively through tumor stages I to IV." (PMID 23800335, 2013). "The ratio of tumor weight to mouse weight indicated that the physical condition of the mice in LEN-NDRG2 group was much better than that of the mice in LEN-LacZ group (F = 39.81, p < 0.001), indicating that the overexpression of NDRG2 could suppress the growth of tumors." (PMID 24146910, 2013). "Since studies in other cancer types demonstrate that high NDRG2 mRNA expression correlates with improved prognosis, future studies could be aimed at developing therapeutic approaches to increase NDRG2 expression in tumor tissue." (PMID 21226903, 2011). "In addition, NDRG2 may act as a tumor suppressor by regulating different molecules, such as TGF-β1 and CD24, which might lead to greater inhibition of HCC." (PMID 21676268, 2011). "Our results showed that NDRG2 may function as a tumor suppressor in CCRCC." (PMID 20673333, 2010). "The tumor site demonstrated a weak inverse correlation with NUPR1 promoter methylation (r = −0.12) and weak positive correlations with GLI1 (r = 0.22) and NDRG2 (r = 0.19) promoter methylation." (PMID 41596413, 2026). "The covariates included in the model were the promoter methylation levels of the NUPR1, NDRG2, and GLI1 genes, as well as age and tumor size." (PMID 41596413, 2026). "NDRG2 promotes c-Myc degradation by inhibiting AKT activation, reduce c-Myc-mediated ASCT2 transcription, ASCT2 catabolises glutamine to supply tumor tissues and promote their progression, ultimately inhibit tumor metastasis by inhibiting glutamine transport." (PMID 41513616, 2026). "Moreover, we showed that Notch signal may be regulated by a tumor suppressor NDRG2." (PMID 37082656, 2023). "Despite growing cell biological and clinical evidence on the relationship between NDRG2 expression and inhibition of TGF-β-mediated tumor metastasis, its molecular mechanism is yet to be identified." (PMID 36012631, 2022). "Tumor TNM stage and age, as well as the expression level of NDRG1 or NDRG2, were included in the nomogram to predict OS (C-index: 0.676), DSS (C-index: 0.741) and PFI (C-index: 0.630)." (PMID 35795037, 2022).
tumor (continued). "The enrolled 371 LIHC tumor samples from the TCGA dataset were stratified into high- and low-expression groups according to NDRG1 or NDRG2 median values (cut-off value of 50%), respectively." (PMID 35795037, 2022). "NDRG2 expression correlates inversely with TNM grade and metastasis in tumor patients and inhibits invasion and metastasis of tumor cells by modulating metastatic cell signaling pathways." (PMID 36012631, 2022). "Genes of interest involved in tumor progression or uterine fibroids, from previous studies, FGFR1, CCND1, PCDH11X, VDR, NDRG2 and INPP4B, are indicated in the volcano plot." (PMID 33807176, 2021). "Finally, since multiple soluble mediators, such as TNF-α, IFN-γ, IL-1β, IL-17, and IL-27, induce PD-L1 expression on tumor cells, it may be reasonable to raise the question of whether the expression of certain mediators among them is downregulated by NDRG2 expression." (PMID 34885221, 2021). "Therefore, our findings clearly indicate that the tumor suppressive role of NDRG2 may be in part due to its inhibitory effect on PD-L1 expression in tumor cells, and that it is intimately involved in directly controlling T cell activity in the tumor microenvironment." (PMID 34885221, 2021). "Mechanistic study indicates that NDRG2 promoted Fbw7-dependent c-Myc degradation by inhibiting Akt activation, and subsequently decreased c-Myc-mediated ASCT2 transcription, in both tumor and NDRG2-knockout MEF cells." (PMID 33162818, 2020). "Since helix α6 in NDRG2 plays a pivotal role in tumor suppressor activity, the unfolded helix α6 region in NDRG3 seems to exert a different function from helix α6 of NDRG2." (PMID 31935861, 2020). "Negative enrichment of FXR in females and downregulation of its target gene Ndrg2 is in line with the human data in patients and confirmed tumor suppressor role of FXR and NDRG2 in human cell lines." (PMID 33182326, 2020). "To verify the NDRG2 regulation of ASCT2 generally occurs in various cancers, we performed the in silico analysis in different types of tumor tissues of the multidimensional data set from TCGA (the cancer genome atlas) and GTEx (Genotype-Tissue Expression)." (PMID 33162818, 2020). "NDRG2 (N-myc downstream-regulated gene 2) is one of the members of NDRG family (NDRG1-4) and it is considered to be a tumor suppressor gene." (PMID 32592365, 2020). "Some of the genes involved include VEGFA (angiogenesis), WNT1 (proliferation), ERBB3 (proliferation), SMAD4 (tumor suppressor), NDRG2 (radioresistance) and EGFR (invasiveness) all leading to tumor aggressiveness." (PMID 30842790, 2019). "This is through the inhibition of the NDRG2/gp130/STAT3 pathway via NDRG2 and subsequently the inhibition of tumor metastasis." (PMID 33817155, 2019). "N-Myc downstream-regulated gene 2 (NDRG2) belongs to the NDRG family and acts as a tumor suppressor gene." (PMID 31523182, 2019). "NDRG2, located at chromosome 14q11.2, is an important member of the NDRG family and recognized as tumor suppressor." (PMID 30348117, 2018). "NDRG2 can reduce the level of receptor gp130 and inactivate its downstream targets STAT3 and ERK1/2, which leads to decreased EMT and tumor metastasis." (PMID 30591630, 2018). "The authors found that the expression of NDRG2 was decreased and miR-181c and LIF increased in human CCA compared with non-tumor tissues." (PMID 29067165, 2017). "NDRG2 down-regulation in patients with late TNM stage, infiltrative growth pattern, poor differentiation grade, nodal/distant metastasis and tumor invasion." (PMID 26506239, 2016). "NDRG2 inhibits CD24 expression and further suppresses tumor adhesion, migration and invasion in HCC." (PMID 26506239, 2016). "The results showed that NDRG2 is covalently modified by SUMO1 at K333, which suppressed anchorage independent adenocarcinoma cell proliferation and tumor growth." (PMID 27072586, 2016). "Thus, the inhibition of angiogenesis may contribute to the anti-tumor effects of NDRG2." (PMID 26506239, 2016).
tumor (continued). "Therefore, NDRG2 works as a recruiter of PP2A to suppress the important signaling pathways for defending against infection or immune responses, and the loss of NDRG2 expression might play an important role in the progression of tumor development." (PMID 26269411, 2015). "The Ad-NDRG2 group that received injections at 2 × 109 PFU achieved a sustained and significant arrest of tumour growth (68% decrease in mean tumour volume on day 21 compared with Ad-LacZ group)." (PMID 24636131, 2014). "The iron chelator Dp44mT up-regulated NDRG2, suppressed epithelial-mesenchymal transition (EMT) and inhibited tumor metastasis in HCC having high metastatic potential." (PMID 25261367, 2014). "To investigate the effects of Ad-NDRG2 on tumor growth in vivo, we injected 1 × 109 PFU Ad-NDRG2, Ad-LacZ, or PBS every 3 days into pre-established human Eca-109 ESCC tumours (approximately 200 mm3) grown in nude mice." (PMID 23800335, 2013). "NDRG2 plays a major role in suppressing HCC metastasis by inhibiting extracellular matrix-based, Rho-driven tumor cell invasion and migration." (PMID 21676268, 2011). "Data showed that NDRG2 expression was decreased in tumor tissues compared to normal adjacent tissues; however, CD24 was enhanced in tumor tissues." (PMID 21676268, 2011). "NDRG2 exerted anti-tumor activity by regulating CD24, a molecule that mediates cell-cell interaction, tumor proliferation and adhesion." (PMID 21676268, 2011). "An evaluation of the NDRG2 mRNA expression level, depending on patient age, was conducted in two groups: in the group of PTC cases in both sexes (primary tumour) at the age till 45 (n = 6) and in the group of cases at the age above 45 (n = 10)." (PMID 20804549, 2010). "It has been proposed that the NDRG2 gene is a candidate TSG, and its expression is low or undetectable in several primary tumour and tumour cell lines." (PMID 19257893, 2009). "Further assessment demonstrated that the expression of necroptosis-related genes, including FADD, MLKL, TLR2, PGAM, HMGB1, CXCL 1, TRAF2, and EZH2, was elevated in tumor tissue, while FAS, RIPK1, RIPK3, TLR3, TNFRSF, ALDH2, and NDRG2 were upregulated in normal intestinal tissues." (PMID 40959081, 2025). "Furthermore, the enhanced expression of NDRG2 remarkably inhibited the suppression of cell proliferation and the protein degradation of AKT and NEMO with the treatment of PRMT5 inhibitors in tumour cells." (PMID 38474089, 2024). "NDRG2 inhibits cell signaling, such as AKT-, NF-κB-, STAT3-, and TGF-β-mediated signaling, to induce tumor metastasis, and induces activation of GSK-3β which has anti-tumor effects." (PMID 36012631, 2022). "Although expression of NDRG2 is not abolished in all carcinomas and tumor tissues, low expression of NDRG2 is closely related to poor prognosis, such as increased metastasis, higher TNM stage, and reduced survival." (PMID 36012631, 2022). "Demographics and tumor characteristics based on the expression of NDRG1 and NDRG2." (PMID 35795037, 2022). "The ASCT2 restoration reversed NDRG2 inhibitory effect on EMT program and tumor metastasis." (PMID 33162818, 2020). "Consistent with this hypothesis, NDRG2 overexpression decreased MC3 cell invasion and migration abilities, and suppressed metastatic tumor formation in lung of nude mice." (PMID 33162818, 2020). "Furthermore, a volcano plot analysis of the entire dataset with MG vs Non-tumor controls revealed significant upheaval in proteins like SPAG9, NDRG2." (PMID 32974197, 2020). "Finally, the effect of the NDRG2/Akt/c-Myc/ASCT2 signaling on glutaminolysis and tumor metastasis were evaluated by functional experiments and clinical samples." (PMID 33162818, 2020). "Thus, we conclude that suppression of ASCT2 is required for NDRG2-dependent inhibition of cell growth, EMT and metastasis in metastatic tumor cells." (PMID 33162818, 2020).